OR3A2 (olfactory receptor family 3 subfamily A member 2)
Description:
Odorant receptor.
Synonyms: OR17-228; OLFRA04; OR228; OR17-14
Gene: Protein-coding gene on chromosome 17 (3,276,177 to 3,386,328, reverse strand). Ensembl gene ENSG00000221882.
Subcellular location: Cell membrane
Pathways (Reactome):
Sensory Perception: Expression and translocation of olfactory receptors
Genetic constraint (gnomAD): Loss-of-function variants: 0 observed, 0.42 expected, observed/expected ratio (o/e) 0, 90% interval 0 to 1.85. That is too few expected variants to judge how well the gene tolerates losing a copy. Missense variants: 256 observed, 281.14 expected, observed/expected ratio (o/e) 0.91, 90% interval 0.82 to 1.01. Synonymous variants: 101 observed, 112.44 expected, observed/expected ratio (o/e) 0.9, 90% interval 0.76 to 1.06.
Homologues: Orthologues: chimpanzee OR3A2 (97% identical), macaque OR3A2 (94% identical), pig OR3A2 (87% identical), dog OR3A2 (80% identical). Paralogues in human: OR3A3 (90% identical), OR3A1 (81% identical), OR1K1 (46% identical), OR1F1 (44% identical), OR1J4 (44% identical), OR7G2 (43% identical), OR7A17 (43% identical), OR7D2 (43% identical), OR7D4 (43% identical), OR1L8 (43% identical), OR1N2 (43% identical), OR7E24 (43% identical), and 116 more.